AGAP2 (ArfGAP with GTPase domain, ankyrin repeat and PH domain 2)
Diseases named in the same sentence as AGAP2 in open-access papers:
AGAP2 is named in the same sentence as 37 diseases in open-access papers, as found by Europe PMC text mining. Sharing a sentence is not in itself a finding about the gene and the disease. The quoted sentences say what the papers report.
glioma (14 papers, 2017 to 2025). A benign or malignant brain and spinal cord tumor that arises from glial cells (astrocytes, oligodendrocytes, ependymal cells). "For example, miR‐199a delivered via MSC‐derived exosomes inhibits glioma cell proliferation and migration by downregulating AGAP2 expression, leading to increased apoptosis in glioma cells." (PMID 40344389, 2025). "MiR-199a is less expressed in glioma tissues than in normal brain tissues, while the GTPase domain, ankyrin repeat and PH domain 2 (AGAP2) are highly expressed." (PMID 36536420, 2022). "It has been shown that miR-199a, when transported by hMSCs derived exosomes, can negatively influence AGAP2 expression, thus preventing proliferation and increasing glioma cell apoptosis." (PMID 36536420, 2022). "The biological function and chemo-sensitivity of U251 cells were evaluated to study the role of miR-199a/AGAP2 in glioma." (PMID 32746854, 2020). "The expression levels of miR-199a and AGAP2 in glioma cells were evaluated using qPCR, immunohistochemistry and Western blotting." (PMID 32746854, 2020). "In our study, we also found that over-expression of miR-199a or AGAP2 silencing was led to inhibition of cell invasion, migration as well as proliferation of glioma cells." (PMID 31386624, 2019). "In summary, this study demonstrates that miR-199a, when delivered by hMSCs via the exosomes, is able to negatively regulate the expression of AGAP2, thereby inhibiting the proliferation and enhancing apoptosis of glioma cells." (PMID 31386624, 2019). "Initially, we found that miR-199a was expressed at low levels, while AGAP2 was highly expressed in glioma." (PMID 31386624, 2019). "The results revealed that the AGAP2 protein expression was higher in the glioma cell lines than that in the NHAs." (PMID 31386624, 2019). "The positive expression of AGAP2 in normal brain tissues and glioma tissues were tested using immunohistochemistry." (PMID 31386624, 2019). "In glioma cells over-expressing miR-199a, the mRNA and protein expression of AGAP2 decreased significantly (p < 0.05)." (PMID 31386624, 2019). "Current studies have revealed that AGAP2 is involved in multiple tumor disease regulation including gliomas." (PMID 31386624, 2019). "The expression pattern of miR-199a and AGAP2 was characterized in glioma tissues and cells using RNA polymerase chain reaction quantification, immunohistochemical staining and Western blot assays." (PMID 31386624, 2019). "Taken together, mesenchymal stem cell-derived exosomal miR-199a can inhibit the progression of glioma by down-regulating AGAP2." (PMID 31386624, 2019). "In this study, we elucidated that miR-199a inhibited the progression of glioma cells via down-regulation of AGAP2." (PMID 31386624, 2019). "The biological behaviors as well as chemosensitivity of U251 cells were assessed to explore the involvement of miR-199a/AGAP2 in glioma." (PMID 31386624, 2019). "Compared with the normal brain tissues, the positive expression rate of AGAP2 in glioma tissues was significantly higher." (PMID 31386624, 2019). "Results showed that AGAP2 was represented as a tan coloration in the cytoplasm and cell membrane and was highly expressed in glioma tissues." (PMID 31386624, 2019). "In order to further understand the upstream regulation mechanism of AGAP2 gene in glioma, Target Scan and other databases were applied to predict the upstream regulatory miRNAs of AGAP2." (PMID 31386624, 2019). "MSC‐derived exosomal miR‐199a downregulates AGAP2 and inhibits glioma progression." (PMID 39950738, 2025). "miR-199 can downregulate the expression of the mTOR signaling pathway to enhance the sensitivity of HCC to DOX.miR-199 also targets the AGAP2 gene and suppresses its expression, enhancing the sensitivity of glioma cells to temozolomide and inhibiting tumor progression." (PMID 39220365, 2024).
glioma (continued). "Similarly, modified MSC-EVs expressing miRNA-199a, which targets AGAP2, were delivered to glioma cells, resulting in the inhibition of glioma development." (PMID 35189894, 2022). "miR-199a was down-regulated and AGAP2 was up-regulated in glioma cells." (PMID 32746854, 2020). "However, the specific mechanism by which AGAP2 exerts an influence on glioma cells still lacks clarification." (PMID 31386624, 2019). "The effect of AGAP2 on the development of glioma cells was verified by AGAP2 gene silencing." (PMID 31386624, 2019). "MiR-199a was poorly expressed in glioma tissue and cells while AGAP2 was highly expressed." (PMID 31386624, 2019). "Herein we hypothesized that miR-199a could be delivered by mesenchymal stem cells to glioma cells through exosomes and thus prevent the glioma development by down-regulating ArfGAP with GTPase domain, ankyrin repeat and PH domain 2 (AGAP2)." (PMID 31386624, 2019). "Moreover, the co-transfection of miR-199a mimic and over-expressed AGAP2 was performed in glioma cells." (PMID 31386624, 2019). "It was shown that over-expression of miR-199a alone could inhibit the expression of AGAP2, and significantly attenuate the proliferation, migration and invasion of glioma cells." (PMID 31386624, 2019). "The results demonstrate that MSCs-derived exosomes could deliver miR-199a to glioma cells to inhibit the progression of glioma by regulating AGAP2." (PMID 31386624, 2019). "Based on the previous reports and findings, we thereby hypothesized that MSCs-derived exosomes could deliver miR-199a to glioma cells and thus prevent the tumorigenic progression of glioma via the down-regulation of AGAP2." (PMID 31386624, 2019). "Among these DEGs, it was noted that AGAP2 was highly expressed in gliomas." (PMID 31386624, 2019). "However, when AGAP2 was over-expressed in the cells transfected with the miR-199a mimic, we found the opposite effect of miR-199a on the glioma cells." (PMID 31386624, 2019). "Thus, this study was aimed at investigating the underlying mechanism of MSCs-derived exosomes delivered miR-199a in glioma, with the involvement of AGAP2." (PMID 31386624, 2019). "Consistent with NS-culture-derived glioma cells with high invasiveness, genes highly expressed in 51A were those encoding markers of neural stem/precursor cells (NANOG, POU3F2, POU5F1, and SALL2), and pro-invasive proteins (AGAP2, EPHA2, FOXM1, PDGFRA, and TNC)." (PMID 29113349, 2017). "Moreover, addition of MSC-exosomal miR-199a increased glioma cell sensitivity to TMZ, and inhibited tumor growth in vivo, by exerting a negative regulative effect on AGAP2 expression." (PMID 32746854, 2020).
glioblastoma (9 papers, 2010 to 2023). The most malignant astrocytic tumor (WHO grade IV). "However, AGAP2 expression is considered ubiquitous and, furthermore, its levels are increased in several cancers (prostate cancer, glioblastoma and other tumours) and are associated to tumour progression." (PMID 30674964, 2019). "AGAP2 with regulatory activity on Arf1 and Arf5 enhances cancer cell survival, migration, and invasion in glioblastoma." (PMID 37182141, 2023). "In addition, it has been demonstrated that Fyn-mediated phosphorylation of AGAP2 promote glioblastoma cell survival as well as adipogenesis and type 2 diabetes development." (PMID 32092977, 2020). "Consistently, AGAP2 was identified as a putative oncogene for glioblastoma multiforme." (PMID 31386624, 2019). "In glioblastoma, it was identified that miR-449b-5p targets phosphatidylinositol 3-kinase enhancer (PIKE, also known as ArfGAP with GTPase domain, ankyrin repeat and PH domain 2 (AGAP2)), which possesses an anti-apoptotic activity." (PMID 34298879, 2021).
prostate carcinoma (4 papers, 2012 to 2020). A carcinoma that arises from epithelial cells of the prostate gland. "Reporter assays have identified the nucleotides -246/+36 in AGAP2 DNA sequence containing the minimal AGAP2 promoter region involved in AGAP2 expression in both chronic myeloid leukemia and prostate cancer human cell lines." (PMID 32092977, 2020). "In this study we have cloned AGAP2 isoform 2 proximal promoter from genomic DNA, and studied the regions that were contributing to AGAP2 expression using prostate cancer cell lines and chronic myeloid leukaemia (CML) cell lines as models." (PMID 30674964, 2019). "Whilst AGAP2 expression in prostate cancer was reported before, this is the first study that links AGAP2 to CML." (PMID 30674964, 2019). "AGAP2 is closely related to prognosis in gastric cancer and prostate cancer." (PMID 32462000, 2020). "We have identified SP1 as a transcription factor bound to AGAP2 promoter and required for AGAP2 expression in two different types of cancer cells (KU812, a chronic myeloid leukaemia cell line; and DU145, a prostate cancer cell line): silencing SP1 decreased AGAP2 protein levels." (PMID 30674964, 2019).
Obesity (3 papers, 2017 to 2024). Accumulation of substantial excess body fat. "Post-translational modifications of AGAP2 regulate AGAP2 expression and activity, and also trigger numerous effects in multiple signaling pathways, modulating cell survival, migration and invasion and contributing to obesity and diabetes development." (PMID 32092977, 2020).
autism (2 papers, 2019 to 2022). Persistent deficits in social interaction and communication and interaction as well as a markedly restricted repertoire of activity and interest as well as repetitive patterns of behavior. "Elevated PI3K-mTOR signaling has been observed in the hippocampus of Fragile X mice and has been linked to elevated levels of PI3K Enhancer (PIKE) encoded by AGAP2, another autism candidate gene with enriched FMRP binding in CA1." (PMID 31860442, 2019).
breast carcinoma (2 papers, 2013 to 2021). "It has also been verified that upregulated exosomal AGAP2-AS1inhibits trastuzumab-induced cytotoxicity in breast cancer cells." (PMID 33972506, 2021).
Hepatic fibrosis (2 papers, 2020 to 2021). The presence of excessive fibrous connective tissue in the liver. "The role of AGAP2 modulating the pro-fibrogenic effects induced by TFGβ1 in liver fibrosis also includes gene regulation processes." (PMID 32092977, 2020). "The present review is focused on the interrelated molecular effects between AGAP2 and TGFβ1 expression, presenting AGAP2 as a new player in the signaling of this pro-fibrotic cytokine, thereby contributing to the progression of hepatic fibrosis." (PMID 32092977, 2020). "Evidence has shown that AGAP2 regulates profibrotic properties in liver fibrosis via TGFβ1." (PMID 34820440, 2021). "AGAP2 seems to be involved in TGFβ1 signaling that could contribute to the progression of hepatic fibrosis, suggesting AGAP2 as a potential new molecular target for liver fibrogenesis." (PMID 34820440, 2021). "In addition, elevated AGAP2 acts as a pathological factor of cancer and liver fibrosis." (PMID 34820440, 2021).
melanoma (2 papers, 2018 to 2020). A malignant, usually aggressive tumor composed of atypical, neoplastic melanocytes. "We constructed a 6-gene signature (IQCE, RFX6, GPAA1, BAHCC1, CLEC2B, and AGAP2) as a novel prognostic marker for predicting the survival of melanoma patients." (PMID 32462000, 2020). "In order to verify whether IQCE, RFX6, GPAA1, BAHCC1, CLEC2B, and AGAP2 were highly expressed in melanoma tissues as predicted, we experimentally confirmed this by qRT-PCR and immunohistochemical staining using melanoma tissues extracted from 10 patients." (PMID 32462000, 2020). "Moreover, genes showing hypermethylation in melanoma such as KRTCAP3, AGAP2, ZNF490, and TTC22 were newly recognized in the present study." (PMID 30719424, 2018). "In addition, immunohistochemistry analysis demonstrated that IQCE, RFX6, GPAA1, BAHCC1, CLEC2B, and AGAP2 were highly expressed in melanoma tissues compared with normal tissue." (PMID 32462000, 2020). "Furthermore, expression of AGAP2, ZNF490, and TTC22 was not decreased in melanoma (data not shown)." (PMID 30719424, 2018).
Alzheimer disease (1 paper, 2020). A progressive, neurodegenerative disease characterized by loss of function and death of nerve cells in several areas of the brain leading to loss of cognitive function such as memory and language. "Further investigation of ADAM9, AGAP2 and PSEN1 levels in human subjects with APP-related disorders could help in understanding Alzheimer’s disease and autism spectrum disorders." (PMID 32612155, 2020).
cardiac hypertrophy (1 paper, 2021). "According to the results in this study, AGAP2 might be correlated with cardiac fibrosis and hypertrophy in Maine Coon cats with HCM." (PMID 34820440, 2021). "However, reports linking AGAP2 with cardiac hypertrophy in cats still require further confirmation." (PMID 34820440, 2021).
hepatocellular carcinoma (1 paper, 2023). A malignant tumor that arises from hepatocytes. "Furthermore, overexpression of Arf GAPs (i.e., AGAP1 and AGAP2) was identified in different cancer types such as breast, colon, lung, ovarian, and hepatocellular carcinoma." (PMID 37182141, 2023).
lung carcinoma (1 paper, 2022). "For example, macrophage-derived exosomes can overexpress ArfGAP with GTPase domain ankyrin repeat and PH domain 2 (AGAP2) antisense RNA 1 (AGAP2-AS1) or underexpress microRNA- (miRNA-) 296 (miR-296) to enhance the antiradiotherapy capability of lung cancer cells." (PMID 35910853, 2022).
skin cancer (1 paper, 2024). "On the other hand, genes resulting from skin and lung metastases were already reported to be associated with diseases in the respective tissues, such as AGAP2 with skin cancer and VSIG8 with respiratory syndromes." (PMID 39409151, 2024).
squamous cell carcinoma (1 paper, 2017). A carcinoma arising from squamous epithelial cells. "AGAP2‐probe methylation seems to be positively correlated with AGAP2 expression in both lung tumour tissue from adenocarcinomas and squamous cell carcinomas (Pearson's correlation coefficient = 0.49, p value 0.025; and Pearson's correlation coefficient = 0.55, p value = 0.15 respectively)." (PMID 27632354, 2017).
uveal melanoma (1 paper, 2023). A melanoma derived from melanocytes of the uveal tract. "Amplified AGAP2 and ASAP1 were associated with impaired OS and progression-free survival in uveal melanoma." (PMID 37182141, 2023).
cancer (19 papers, 2010 to 2024). A tumor composed of atypical neoplastic, often pleomorphic cells that invade other tissues. "Amongst them, 33 (25.2%) have been reported as GBM-related (e.g., EGFR, PTEN, MTOR) and 29 (22.1%) as cancer-associated genes (e.g., AGAP2, SOX2)." (PMID 38724522, 2024). "In cancer cells, this positive feedback activation loop between AGAP2 and Akt enhances AGAP2 phosphorylation and promotes its association with UNC5B, thereby inhibiting the UNC5B-dependent programmed cell death." (PMID 36611866, 2022). "The increase of AGAP2 levels is associated with pathologies as cancer and fibrosis." (PMID 32092977, 2020). "Interaction between AGAP2 and active Akt further enhances Akt activity leading to human cancer cell survival and promoting cancer cell invasion and migration." (PMID 36611866, 2022). "Arf GTPase-activating protein-2 (AGAP2) is able to mediate endosomal trafficking and is found to be over-expressed in many human cancers." (PMID 31386624, 2019). "Among the numerous possible candidates, we picked out the ones overexpressed in cancers and proliferation- and metastasis-associated genes, including NOTCH2, FGFR1, CSF1, AGAP2, CREB1, for further analysis." (PMID 24614175, 2014). "And it was proposed that ATRA might lead to the recruitment of PCAF and perhaps increased SP1 binding to AGAP2 promoter, thereby leading to increased AGAP2 levels in cancer cells." (PMID 32092977, 2020). "Moreover, the protein expression of AGAP2 was detected by Western blot analysis in NHAs and cancer cell lines." (PMID 31386624, 2019). "The AGAP2 gene is overexpressed in cancer cells, and promotes cancer cell invasion." (PMID 27632354, 2017). "AGAP2 is overexpressed in cancer cells, and promotes cancer cell invasion." (PMID 26863628, 2016). "Given the key role of HOX genes in cell differentiation, function, and cancer as well as AGAP2 as a proto-oncogene, additional work needs to be conducted to determine if changes in the expression of these genes could alter the histology and function of the pancreas tissue." (PMID 34573497, 2021). "AGAP2 phosphorylation by kinases such as Fyn, AMP-K and cyclin dependent kinase 5 contributes to regulation of cancer progression." (PMID 36611866, 2022). "Interestingly, AGAP2 might be regulated by growth factors since it has been demonstrated that the addition of epithelial growth factor (EGF) triggers AGAP2 phosphorylation on both Y682 and Y774 residues attenuating the apoptotic cleavage of AGAP2 in human cancer." (PMID 32092977, 2020). "Thus, we now know that AGAP2 is involved in different functions including cell proliferation and survival, remodeling of actin cytoskeleton, or membrane trafficking, and that these functions turn AGAP2 into a potential target in different pathologies such as cancer and fibrosis." (PMID 32092977, 2020). "Indeed, AGAP2, which acts on ARF1 and ARF5, promotes cancer cell survival, migration and invasion in gliobastomas." (PMID 32426352, 2020). "Additionally, the authors observed that the treatment of cells of these types of cancer with the polyphenol curcumin, leads to a decrease in ATRA-mediated AGAP2 expression." (PMID 32426352, 2020).
tumor (10 papers, 2012 to 2024). "Six characteristic genes (IQCE, RFX6, GPAA1, BAHCC1, CLEC2B, and AGAP2) were selected by random forest feature selection, many of which have been reported to be associated with tumor progression." (PMID 32462000, 2020).
psychiatric disease (1 paper, 2017). "This reflects the diverse sets of Agap2 interactors implicated in contributing to psychiatric disease as the majority of interactors that contribute to the similar levels of enrichment between PSD and non-PSD complexes are unique to Agap2 based on its subcellular location." (PMID 28706196, 2017).
AGAP2 also shares sentences with these, for which no sentence is quoted: fragile X syndrome (3 papers); chronic myeloid leukaemia (2); colorectal cancer (2); acute myeloid leukemia (1); adenocarcinoma (1); anaplastic large cell lymphoma (1); autism spectrum disorder (1); brain tumors (1); colonic diseases (1); diabetes (1); endometrial carcinoma (1); gastric cancer (1); Hyperinsulinemia (1); hypertrophy (1); liver cancer (1); lung adenocarcinoma (1); osteosarcoma (1); sarcoma (1); squamous cell lung carcinoma (1).